LEPR (leptin receptor)
Description:
Receptor for hormone LEP/leptin (Probable). On ligand binding, mediates LEP central and peripheral effects through the activation of different signaling pathways such as JAK2/STAT3 and MAPK cascade/FOS. In the hypothalamus, LEP acts as an appetite-regulating factor that induces a decrease in food intake and an increase in energy consumption by inducing anorexinogenic factors and suppressing orexigenic neuropeptides, also regulates bone mass and secretion of hypothalamo-pituitary-adrenal hormones (By similarity). In the periphery, increases basal metabolism, influences reproductive function, regulates pancreatic beta-cell function and insulin secretion, is pro-angiogenic and affects innate and adaptive immunity. Control of energy homeostasis and melanocortin production (stimulation of POMC and full repression of AgRP transcription) is mediated by STAT3 signaling, whereas distinct signals regulate NPY and the control of fertility, growth and glucose homeostasis. Involved in the regulation of counter-regulatory response to hypoglycemia by inhibiting neurons of the parabrachial nucleus. Has a specific effect on T lymphocyte responses, differentially regulating the proliferation of naive and memory T -ells. Leptin increases Th1 and suppresses Th2 cytokine production (By similarity). [Isoform A]: May transport LEP across the blood-brain barrier. Binds LEP and mediates LEP endocytosis. Does not induce phosphorylation of and activate STAT3. [Isoform E]: Antagonizes Isoform A and isoform B-mediated LEP binding and endocytosis.
Synonyms: LEP-R; OB-R; CD295; OBR; LEPRD; huB219
Tractability: Small molecule: a structure with a bound ligand is known. Antibody: a drug acting on it is in phase 2 or 3 trials; UniProt places it where antibodies can reach, with high confidence; UniProt predicts a signal peptide or a membrane-spanning region; its Gene Ontology location is reachable by antibodies, with medium confidence. PROTAC: ubiquitination databases record sites on it. Other modalities: an approved drug acts on it.
Safety:
Unwanted effects reported when the protein is acted on. In parentheses: how it was acted on, where the effect was seen, and who reports it.
weight gain (source: ClinPGx)
Gene: Protein-coding gene on chromosome 1 (65,420,652 to 65,641,559, forward strand). Ensembl gene ENSG00000116678.
Subcellular location: Cell membrane; Basolateral cell membrane; Secreted (Isoform E)
Subcellular location (Human Protein Atlas): Vesicles; Basal body; Cytosol; Plasma membrane; Primary cilium
Pathways (Reactome):
Signal Transduction: Signaling by Leptin
Gene Ontology:
Molecular function: leptin receptor activity; peptide hormone binding; protein binding; cytokine binding; cytokine receptor activity; transmembrane signaling receptor activity; signaling receptor activity
Biological process: angiogenesis; cell surface receptor signaling pathway via STAT; leptin-mediated signaling pathway; negative regulation of autophagy; regulation of transport; bone growth; cell surface receptor signaling pathway; cytokine-mediated signaling pathway; energy homeostasis; energy reserve metabolic process; glucose homeostasis; multicellular organism development; positive regulation of cell population proliferation; positive regulation of cold-induced thermogenesis; regulation of bone remodeling; regulation of cytokine production involved in inflammatory response; regulation of feeding behavior; response to leptin; sexual reproduction; T cell differentiation; transport across blood-brain barrier; phagocytosis; system development
Cellular component: basolateral plasma membrane; plasma membrane; receptor complex; external side of plasma membrane; extracellular region; membrane
Genetic constraint (gnomAD): Loss-of-function variants: 53 observed, 113.09 expected, observed/expected ratio (o/e) 0.47, 90% interval 0.38 to 0.59. The upper end of that interval is the gene's LOEUF score, 0.59, which puts it in group 2 of 6, group 1 being the genes least tolerant of losing a copy. Missense variants: 1,198 observed, 1,410.5 expected, observed/expected ratio (o/e) 0.85, 90% interval 0.81 to 0.89. Synonymous variants: 440 observed, 486.44 expected, observed/expected ratio (o/e) 0.9, 90% interval 0.84 to 0.98.
Homologues: Orthologues: chimpanzee LEPR (99% identical), macaque LEPR (96% identical), pig LEPR (84% identical), dog LEPR (83% identical), rabbit LEPR (82% identical), rat Lepr (76% identical), mouse Lepr (75% identical), guinea pig LEPR (70% identical), tropical clawed frog lepr (40% identical), zebrafish lepr (24% identical). Paralogues in human: IL6ST (11% identical), LIFR (11% identical), OSMR (10% identical), IL31RA (9% identical), CSF3R (9% identical), IL12RB2 (9% identical), CRLF1 (7% identical), IL12RB1 (7% identical), PRLR (7% identical), IL23R (6% identical), IL27RA (6% identical), GHR (5% identical), and 11 more.
Diseases named in the same sentence as LEPR in open-access papers:
LEPR is named in the same sentence as 318 diseases in open-access papers, as found by Europe PMC text mining. Sharing a sentence is not in itself a finding about the gene and the disease. The quoted sentences say what the papers report.
Obesity (971 papers, 2005 to 2026). Accumulation of substantial excess body fat. "On the other hand, leptin and leptin receptor polymorphisms have been related to obesity, which has been ascribed to the relationship between body weight and eating behaviors." (PMID 40559461, 2025). "Seven publications reported outcomes of MBS in patients with obesity caused by rare variants in LEPR, MC4R, NCOA1, PCSK1, POMC, SH2B1, or SIM1." (PMID 40560452, 2025). "Leptin receptor and proopiomelanocortin deficiency are monogenic obesity disorders caused by bi-allelic variants in LEPR and POMC or PCSK1, respectively." (PMID 40564803, 2025). "Obesity is associated with chronically high leptin levels but impaired hypothalamic and hippocampal leptin receptor signaling." (PMID 41516046, 2025). "The db/db mouse is an excellent model for severe obesity-related metabolic disease, but it is characterized by leptin resistance by definition due to leptin receptor deficiency." (PMID 40639664, 2025). "The primary data available focus on the established association between the leptin receptor gene polymorphism rs12131454 (Glu223Arg) and the development of type 2 diabetes mellitus, metabolic syndrome, and obesity." (PMID 40361972, 2025). "There are several monogenetic and polygenetic experimental models of obesity: some notable examples include leptin-deficient mice (ob/ob), leptin-receptor deficient mice (db/db) and the New Zealand obese mouse strain (NZO)." (PMID 40837095, 2025). "Consistently, DIO mice show decreased hypothalamic LepR mRNA despite elevated leptin levels, suggesting that diminished receptor responsiveness contributes to obesity-associated leptin resistance." (PMID 41516046, 2025). "Female mice with heterozygous leptin receptor deficiencies were administered a 45 kcal% high-fat diet to establish a GDM model incorporating both obesity and genetic factors." (PMID 40774956, 2025). "The genetic causes of obesity include monogenic obesity that arises due to mutations in a single gene, specifically mutations in the leptin receptor." (PMID 41009702, 2025). "Leprdb/db (db/db) mice provide a commonly used model of T2DM due to mutation in the leptin receptor gene, with susceptibility to obesity and insulin resistance." (PMID 40617804, 2025). "EMANATE aims to extend the indications of setmelanotide beyond biallelic POMC, PCSK1, and LEPR deficiencies, potentially addressing a broader spectrum of genetically driven obesity." (PMID 41212412, 2025). "db/db mice exhibit a mutation in the leptin receptor gene, leading to impaired leptin signaling and the development of early-stage obesity." (PMID 40024983, 2025). "Due to a leptin receptor mutation, db/db mice develop obesity and hyperglycemia beginning at approximately three weeks of age." (PMID 40647186, 2025). "In terms of the connection between LEP and LEPR gene variants and obesity, there is limited information regarding the presence of MetS." (PMID 39136228, 2025). "Hyperglycaemia in db/db mice is caused by mutation in the leptin receptor, which affects hypothalamic responses and leads to obesity and insulin resistance." (PMID 40617804, 2025). "ICR mice lack the leptin receptor mutation present in db/db mice, which makes db/db mice a more prominent experimental model for obesity and hyperglycemia, closely resembling late-stage human T2DM." (PMID 40599352, 2025). "These mice carry gene mutations, which lead leptin receptor cannot be code normally, and cause obesity and diabetes symptoms." (PMID 40125968, 2025). "Patients with leptin receptor mutations experience an extremely early onset of obesity, which has a direct effect on hyperphagia, insulin sensitivity, glucose intolerance, metabolic disorders, and recurring infections." (PMID 41009702, 2025). "In another model characterized by obesity, the leptin receptor–deficient db/db mouse, BP dipping was reduced along with an elevated 24-hour BP." (PMID 39812779, 2025).
Obesity (continued). "Insulin resistance and obesity induced by diet or genetic mutation of the leptin receptor in mice leads to a decrease in synaptic density of hippocampal dentate granule neurons and compromised hippocampal synaptic plasticity." (PMID 40137124, 2025). "Obese Zucker rats that mimic monogenic human obesity manifest similar clinical complications that have been reported in patients with leptin receptor mutations." (PMID 41009702, 2025). "There are studies suggesting a gene-gene interaction between the LEP and LEPR variants in a genetic susceptibility to the development of obesity." (PMID 40152811, 2025). "LEPR polymorphism has been shown to be associated with insulin resistance, obesity, dyslipidemia, and increased serum leptin levels in women with PCOS due to high-fat content." (PMID 40410881, 2025). "In particular, leptin deficiency was associated with the development of severe obesity in mice, and the genes encoding leptin and the leptin receptor (LEPR) were further identified and cloned." (PMID 40689079, 2025). "Leptin/leptin receptor signaling can promote obesity-associated asthma by inducing M1 macrophage polarization, leading to nonallergic asthma characterized by excessive neutrophil infiltration in the airways." (PMID 40319236, 2025). "Knockout of LepR in these NO neurons results in hyperphagic obesity, reduced energy expenditure, and hyperglycemia similar to what is observed in global LepR-deficient mice." (PMID 41321496, 2025). "Leptin receptor mutations have been associated with metabolic abnormalities, such as obesity, disruption of energy homeostasis, dyslipidaemia, and hyperglycaemia." (PMID 40429924, 2025). "For example, polymorphisms in the FTO, MC4R, LEP, and LEPR genes have been significantly associated with obesity and hypertriglyceridemia in Mexican children aged 4–13 years (n = 718)." (PMID 40647298, 2025). "We show that db/db mice, which have a spontaneous mutation in the leptin receptor that promotes obesity and type 2 diabetes, had reduced liver GAA activity." (PMID 40108792, 2025). "Genetic mutations resulting in variants of LepR, such as K109R, Q223R, and K656N, have an increased association with obesity." (PMID 40522819, 2025). "The parents of 134 of these children were also enrolled to examine the relationship of leptin and leptin receptor polymorphisms with obesity." (PMID 40559461, 2025). "The deficiency in LepR will result in hyperleptinemia leading to hyperphagia and a decrease in energy expenditure, and subsequently in an increased degree of obesity associated with increased lipid deposition in the muscle, liver and other tissues." (PMID 39273348, 2024). "The role of these populations in leptin signalling has also been evaluated and, whereas a knockout of the LepR in AGRP/NPY neurons of adult mice causes extreme obesity, deletion of the LepR from adult POMC neurons has only a minimal effect." (PMID 39478220, 2024). "It is worth mentioning that there are also mouse models with EC-specific LEPR deficiency, in which the animals develop obesity only when high fat diet is introduced." (PMID 39317805, 2024). "Db/db mice, characterised by mutations in the leptin receptor gene, exhibit a disrupted leptin signalling pathway, resulting in obesity, insulin resistance, hyperglycaemia, lipid metabolism disorders, inflammation, and oxidative stress." (PMID 38378566, 2024). "In NAFLD patients, LEPR polymorphism was found to be associated with obesity parameters, insulin resistance and blood glucose levels." (PMID 38169083, 2024). "Leptin-receptor-deficient mice with obesity and diabetes (BKS db/db) were either untreated or administered with semaglutide for 11 weeks." (PMID 38474208, 2024). "The rs1137101 (A > G) polymorphism of the LEPR gene was associated with obesity, high leptin level due to disruption of LEPR signaling and greater waist circumferences." (PMID 39203789, 2024).
Obesity (continued). "Leptin receptor-deficient db/db mice are a common model of Type II diabetes, developing hyperglycemia and obesity as well as hyperphagia." (PMID 38596458, 2024). "These mice are commonly used to study obesity and T2D due to their genetic mutations leading to leptin deficiency (ob/ob) or leptin receptor dysfunction (db/db), which result in insulin resistance, obesity, and eventually, DKD." (PMID 39274263, 2024). "To obtain an animal model representative of the obesity characteristic of the majority of IIH patients, we employed a female rat model of obesity originating from a genetic deficiency in the leptin receptor." (PMID 38273331, 2024). "An uncommon obesity condition with mendelian inheritance occurs in humans when the leptin receptor gene (LEPR) is mutated." (PMID 39203789, 2024). "In Brazilian pregnant women, the LEPR rs1137101 genetic variant was associated with pregestational overweight or obesity." (PMID 38474283, 2024). "The LEPR rs1137101 analysis highlights a gradient effect in which the GG genotype is associated with higher obesity metrics and emotional eating scores, whereas the AA genotype is linked to leaner body compositions and lower emotional eating behaviors." (PMID 39203789, 2024). "Leptin is widely recognized as a cytokine, pleiotropic hormone, and an obesity-associated adipokine that upon binding to its leptin receptor, regulates energy metabolism and appetite." (PMID 38418632, 2024). "It has previously been reported that the obesity-prone Iberian pig has a polymorphism of the leptin receptor gene which affects leptin sensitivity, and it would be interesting to study if this is also the case in Göttingen Minipigs." (PMID 38427692, 2024). "In this study, we used a genetically induced mouse model of type 2 diabetes with db/db mice, which have a mutation in the leptin receptor gene (LepR) and are characterised by obesity, decreased insulin receptor sensitivity and elevated levels of blood glucose." (PMID 37979047, 2024). "Some of the other well-known genetic murine obesity models include the db/db (leptin receptor-deficient) and the lethal yellow agouti model (ectopic ubiquitous expression of the agouti protein)." (PMID 38542451, 2024). "Mutations in LEPR can cause receptor deficiency, leading to severe obesity and hyperphagia due to improper leptin signaling." (PMID 39777073, 2024). "Genetic susceptibility to obesity concerns only a fraction of the population and is the resultant of rare mutations in single genes (e.g., LEPR, PCSK1) or chromosomal abnormalities (e.g., Prader–Willi syndrome)." (PMID 39125772, 2024). "In animal models of obesity with mutations in the ob gene or LepR, heart failure was commonly observed." (PMID 38397015, 2024). "Many LEPR variants are currently under investigation for their possible link to leptin resistance and obesity, the most important are rs1137100 and rs1137101." (PMID 39203789, 2024). "The LEPR gene encodes for six different isoforms (LEPR a–f), among which the LEPR-b receptor has been mostly associated with severe forms of monogenic obesity." (PMID 38397265, 2024). "Db/db mice, which are considered a model of type 2 diabetes, are homozygous for the spontaneous db mutation in the leptin receptor gene (Leprdb) and develop chronic hyperglycemia, insulin resistance and obesity." (PMID 38237896, 2024). "The evaluation of deletions and duplications, in regions associated with obesity, is possible by assessing genes LEPR, POMC, SIM1, LEP, MC4R, MC2R, and MC3R, and in the 16p11.2 region by MLPA." (PMID 39458556, 2024). "For this, we used db/db.BKS mice which during the first three months develop massive obesity and uncontrolled diabetes due to a mutation in the leptin receptor." (PMID 37279200, 2023).